MMP9 (matrix metallopeptidase 9)
Diseases named in the same sentence as MMP9 in open-access papers (continued):
Sharing a sentence is not in itself a finding about the gene and the disease.
gastric cancer (continued). "Furthermore, the preoperative serum levels of the MMP-9 protein in the gastric carcinoma tissue were correlated with the tumor-node-metastasis stage and occurrence of lymph node metastasis (P<0.01)." (PMID 25621068, 2015). "MMP-9 is associated with the growth, invasion and metastasis of gastric carcinoma, however, there are few reports regarding preoperative serum levels of MMP-9 in gastric carcinoma." (PMID 25621068, 2015). "In addition, it has been reported that MMP-9 plays an important role in gastric cancer recurrence and prognosis." (PMID 25207654, 2014). "Recent studies suggested that RNAi-mediated down-regulation of CD147 decreased cell proliferation, MMP-2 and MMP-9 activities and the invasive potential of SGC7901 cells, which support our results demonstrating the association of CD147 with gastric cancer invasion and metastasis." (PMID 24979746, 2014). "Further insights into the functional and clinical implications of FENDRR and its targets FN1 and MMP2/MMP9 may help with the treatment of gastric cancer." (PMID 25167886, 2014). "Moreover, ALDH1A1 was significantly correlated with MMP-9 among 216 gastric cancer tissues (P < 0.001)." (PMID 25253129, 2014). "In addition, the level of HSP60 was significantly correlated with MMP-9 in 223 gastric carcinoma specimens." (PMID 25207654, 2014). "In addition, the expression of nuclear pSTAT3 and cytoplasmic MMP9 were found in 61 of 255 (24%) and 46 of 255 (18%) of gastric cancer specimens, respectively." (PMID 23402362, 2013). "Similarly, BMP2 has been shown to increase the expression of MMP9 in gastric cancer cells through AKT, ERK and NF-κB signaling cascades." (PMID 24053318, 2013). "In addition, both NF-κB activation and STAT3 activation were positively correlated with MMP9 in gastric cancer tissues (P = 0.001 and P = 0.022, respectively), decreased E-cadherin expression and increased Snail and MMP9 expressions in cultured cells." (PMID 23402362, 2013). "Therefore, we investigated the relationship of HSP90 and MMP-9 protein expression in gastric cancer." (PMID 23638161, 2013). "In conclusion, these results suggest that coronin 3 may promote the invasion and metastasis of gastric cancer both in vitro and in vivo by regulating the expression of MMP-9 and cathepsin K." (PMID 22974233, 2012). "In the present study, we have provided clear evidence that coronin 3 is highly expressed in metastatic gastric cancer tissues and that coronin 3 can promote gastric cancer metastasis, at least in part by up-regulating cathepsin K and MMP9 expression and down-regulating TIMP2 expression." (PMID 22974233, 2012). "The data showed that the expression levels of MMP-2 and MMP-9 significantly decreased in the CTGF knockdown stable cell lines (PSC1 and PSC2), suggesting that this downregulation of MMP-2 and MMP-9 contributed to the reduced invasion of the CTGF knockdown stable gastric cancer cells." (PMID 21955589, 2011). "We suggest that silibinin may be an effective therapeutic drug for anti-cancer therapy by preventing cancer metastasis through the down-regulation of MMP-9 expression in gastric cancer." (PMID 19924065, 2009). "Silibinin may be an effective additive to anti-metastatic therapy by preventing cancer metastasis through the down-regulation of MMP-9 in gastric cancer." (PMID 19924065, 2009). "And levels of MMP-2 and MMP-9 are also found elevated in plasma of gastric cancer patients." (PMID 19586554, 2009). "A decade ago, we were the first to report that the levels of matrix metalloproteinase (MMP)-2 and MMP-9 in human gastric carcinoma tissues were enhanced and related to the survival of the patients, using a simple but laborious zymography technique in a relatively small group of patients." (PMID 16538217, 2006). "In gastric cancer (GC), LINC01296 competitively binds to miR-122 to up-regulate matrix metalloproteinase-9 (MMP-9) and promote the progression of GC." (PMID 39901673, 2025).
gastric cancer (continued). "LGMN either directly or indirectly affects MMP-9 in gastric cancer, causing it to gradually change from an inactive protease form into an active MMP-9 form that inhibits the activity of the extracellular matrix and encourages the spread of gastric cancer cells." (PMID 36825203, 2023). "Consistent with decreased MMP-9 levels, C-PAC and AFG decreased expression of L1CAM in JHAD1 cells, a neuronal adhesion protein linked to metastasis and chemoresistance, and is overexpressed in many solid tumor cancers including esophageal squamous cell carcinoma and gastric cancer." (PMID 35267943, 2022). "Therefore, agents with the ability to suppress MMP-9 expression may be useful for the development of treatment strategies for gastric cancer." (PMID 35563563, 2022). "The possible mechanisms of the components of the Zhishi-Baizhu herb pair in treating gastric cancer might be related to luteolin and naringenin, which intervened with the targets AKT1, MMP9, IL-6, CCND1, BCL2, MTOR, and MDM2, and are linked with the PI3K-Akt and IL-17 signaling pathways." (PMID 34899944, 2021). "Importantly, MMP9 is one of the downstream target genes of SMYD3 (SET and MYND domain containing protein 3), the histone H3-K4 di-/tri- and H4-K5-methyltransferase, and overexpression of SMYD3 can induce MMP9 expression in human tumor models, e.g., gastric cancer." (PMID 34943943, 2021). "Furthermore, we found an overexpression of MMP-9, that promotes tumor invasion and is associated with poor prognosis in gastric cancer, ANXA1 and ANXA4, overexpressed in gastric cancer and associated with proliferation, AREG, that promotes malignant progression in several types of cancer." (PMID 34012923, 2021). "Additionally, miR-211 acted as a tumor suppressor and inhibited EMT by targeting MMP9 expression and may be a potential target of gastric cancer treatment." (PMID 34943943, 2021). "Moreover, the interaction of monocytes with fibronectin modulates their expression of matrix metalloproteinases (MMPs), especially MMP9, when they are co-cultured with gastric carcinoma-derived cancer cells, whereas depletion of fibronectin results in diminished MMP9 production." (PMID 33466303, 2021). "Thus, we could speculate a TRPM2-Akt-Rac1 axis in the modulation of MMP-9 expression in gastric cancer." (PMID 33132914, 2020). "Moreover, HER2 can promote gastric cancer malignancy by regulating MMP-9." (PMID 33233689, 2020). "Moreover, the activity of MMP-9 increased by Tid1 knockdown in the NUGC-3 gastric cancer cells." (PMID 33233689, 2020). "Up regulation of LINC01296 in gastric cancer cells and cell lines resulted to aggravate GC development using the miR-122/MMP-9 axis." (PMID 32856843, 2020). "Finally, silencing of AEG‐1 expression not only inhibited tumour growth in parallel with downregulation of eIF4E, MMP‐9 and Twist expression in a xenograft nude mouse model, but also suppressed lymph node and peritoneal metastasis of gastric cancer in an orthotopic nude mouse model." (PMID 28661037, 2017). "Therefore, the correlation of FOXO6 and MMP-9 expression was evaluated in gastric cancer patients." (PMID 28404958, 2017). "In addition, spondin-2 was positively correlated with MMP-9 protein expression in gastric cancer." (PMID 28060752, 2017). "In addition, spondin-2 was positively correlated with MMP-9 among 174 gastric cancer samples." (PMID 28060752, 2017). "ING5 overexpression was in vitro found to decrease migration, invasion and lamellipodia formation with MMP-9 hypoexpression, and in vivo suppressed lung metastasis of gastric cancer cells, suggesting that ING5 might inhibit invasion and metastasis of gastric cancer by reducing MMP-9 expression." (PMID 25980581, 2015). "In conclusion, the present study demonstrated that MMP-9 protein levels in the preoperative serum and mRNA expression in carcinoma tissue were higher than the healthy controls, and were correlated with specific clinicopathological features of gastric carcinoma." (PMID 25621068, 2015).
gastric cancer (continued). "Furthermore, the present study identified that patients with gastric carcinoma exhibited higher preoperative peripheral serum MMP-9 levels compared with the control groups, and demonstrated that the serum MMP-9 levels correlated with the TNM stage and occurrence of lymph node metastasis." (PMID 25621068, 2015). "Therefore, we also investigated the relationship of HSP60 and MMP-9 protein in gastric cancer." (PMID 25207654, 2014). "Moreover, HSP60 was significantly correlated with MMP-9 among 223 gastric cancer tissues (P<0.001)." (PMID 25207654, 2014). "Therefore, we also investigated the relationship of ALDH1A1 and MMP-9 protein in gastric cancer." (PMID 25253129, 2014). "In addition, ALDH1A1 was significantly correlated with MMP-9 in 216 gastric carcinoma specimens." (PMID 25253129, 2014). "Moreover, HSP90 was significantly correlated with MMP-9 among 322 gastric cancer tissues (P<0.001)." (PMID 23638161, 2013). "Moreover, IL-1β promoted migration and invasion of the gastric cancer cells may be mediated by matrix metalloproteinase-9 (MMP9) as other searchers reported." (PMID 24223129, 2013). "Therefore, we speculate that MMP9 can be induced by many other pathways independent on NF-κB/STAT3 signaling pathway in gastric cancer." (PMID 23402362, 2013). "We performed cDNA microarray analysis to identify the downstream target genes of SOX2 in gastric cancer cells, and found that many tumor-associated genes exhibited significant changes in expression after SOX2-overexpression (e.g., LTF, PPP2R1B, TGFBR2, SERPINE1, MMP9, HMGA1 and SOX9)." (PMID 21304604, 2011). "MMP9 is known to be overexpressed many epithelial tumors including gastric tumors and its involvement in the breakdown of extracellular matrix could explain its role in gastric cancer progression and formation of metastases." (PMID 20187983, 2010). "An association between MMP-9/NGAL complex and gastric cancer has also been suggested since complex expression in tumor tissue of gastric cancer patients was highly associated with worse survival and was related to the histological and genetic typing of gastric cancer." (PMID 19889214, 2009). "Furthermore, EMMPRIN transfection of tumour cells or treating tumour cells with the recombinant protein increased the expression of MMPs, especially MMP-2, as also evidenced by the positive correlation of EMMPRIN expression with MMP-2 and MMP-9 expression in our cases of gastric carcinoma." (PMID 17088917, 2006). "However, the relatively high MMP-9 levels in early gastric carcinomas also might affect the relation between MMP-9 and prognosis, especially in our extended follow-up study using tumour-related survival." (PMID 16538217, 2006). "It is well established that MMP-2, MMP-9, and MMP-11 contribute to the remodeling of the tumor microenvironment (TME) in gastric cancer through both structural and functional mechanisms." (PMID 40906383, 2025). "In cultured human gastric cancer cells, EA treatment hindered the acidic microenvironment-induced upregulation of MMP7 and MMP9 mRNAs as well as tumor migration and invasion." (PMID 40386045, 2025). "Studies indicate that the expression of both MMP-9 and MMP-2 correlates with the expression of LOX in gastric cancer biopsies." (PMID 40906383, 2025). "In gastric cancer cells (AGS and NCI-N87), Tax inhibited colony formation and wound healing, leading to reduced MMP-2 and MMP-9 expression." (PMID 40563423, 2025). "AQP3 serves a key role in the progression and metastasis of various types of cancer: AQP3 can upregulate matrix metalloproteinases (MMP1, MMP2 and MMP9) and induce EMT by activating the PI3K/AKT signaling in gastric cancer." (PMID 39611488, 2025). "Han and Tsai found that inhibiting the expression of VEGF in gastric cancer cells can reduce the expression of MMP2 and MMP9." (PMID 40563539, 2025).
gastric cancer (continued). "A study investigating the impact of ERα expression in CAFs in gastric cancer confirmed increased expression of matrix metalloproteinase-2 (MMP2) and matrix metalloproteinase-9 (MMP9)." (PMID 41301715, 2025). "The potential of andrographolide lies in its ability to impede the progression of gastric cancer by suppressing MMP-2 and MMP-9 activities simultaneously enhancing TIMP-1 and TIMP-2 expression." (PMID 39583105, 2024). "SETDB1 mediates the malignant biological behaviour of gastric cancer by interacting with ERG and enhancing the promoter activity of CCND1 and MMP9." (PMID 38317200, 2024). "Various anti-gastric cancer-related signalling pathways, such as Src/MAPKs/AP-1 and TLR4/NF-kB/MMP-9 are also controlled by andrographolide." (PMID 39583105, 2024). "In gastric cancer cells, HMGB3 promotes cell invasion and migration by modulating MMP2 and MMP9 expression." (PMID 39684631, 2024). "We noticed an increase in MMP9 and a decrease in CASP3 when comparing the gene expression patterns of healthy stomach tissue with those of stomach cancer tissue." (PMID 38769413, 2024). "Reducing the expression of HMGB3 leads to inhibition of invasion and migration of gastric cancer cells by suppressing the activation of MMP2 and MMP9." (PMID 39062899, 2024). "CXCR4, SPP1, CXCL1, MMP9, and TIMP1 were up-regulated and NFE2L2 was down-regulated in gastric cancer cell lines compared with control." (PMID 38221932, 2024). "The expression levels of MMP9 and CASP3 are significantly correlated with the overall survival time of patients with gastric cancer." (PMID 38769413, 2024). "The differences in the expression of hub genes, PTGS2, MMP9, MMP2, and CXCR4 genes were higher than normal gastric tissues in gastric cancer, and PPARG gene was lower than normal gastric tissues." (PMID 38457601, 2024). "In gastric cancer, the downregulation of LOX expression can downregulate the expression of MMP-2 and MMP-9 in cancer cells." (PMID 39132501, 2024). "Mast cells promote the development of gastric cancer by releasing angiogenic (VEGF-A, CXCL8, MMP-9) and lymphangiogenic components (VEGF-C, VEGF-F)." (PMID 36923439, 2023). "Even more, in gastric cancer cell lines, AQP3 overexpression upregulated matrix metalloproteinases MT MMP1, MMP2, and MMP9, while its silencing decreased them via a PI3K/Akt-dependent manner." (PMID 37175840, 2023). "In gastric cancer cell (AGS) models, overexpression of MEG3 inhibited epithelial-mesenchymal transition (EMT) by decreasing MMP-3 and MMP-9 levels and thereby inhibiting cell migration." (PMID 36968595, 2023). "In this regard, it was shown that GPR176 silencing reduced the expression of MMP9, which explained GPR176’s effects of promoting the invasion and metastasis of gastric cancer cells." (PMID 37584712, 2023). "By up-regulating the expression of MMP-9, SETDB1 can promote the occurrence and metastasis of gastric cancer." (PMID 37274740, 2023). "Under acidic conditions, gastric cancer cells become more invasive, with elevated expression of MMP-7 and MMP-9." (PMID 38002335, 2023). "We further analyzed the genes (such as MMP9, HMGA2, and KPNB1) in the gastric cancer cohort (TCGA‐STAD), and found that DR5 was positively correlated with them and higher than DR4." (PMID 37879960, 2023). "Downregulating the expression of lncRNA-PVT1 can reverse the promotion of MMP9 overexpression on the invasion of LCC, and downregulating its expression can reverse the promotion of MMP9 silencing on the invasion of gastric cancer cells." (PMID 36164442, 2022). "Sulforaphane suppresses the nicotine-induced MMP-9 by inhibiting ROS-mediated MAPK (p38 MAPK, Erk1/2)/AP-1 and ROS-mediated NF-κB signaling axes, which in turn inhibit cell invasion in human gastric cancer AGS cells." (PMID 35563563, 2022). "TNF-induced MMP-9 mRNA and protein expression in SNU216 and SNU668 gastric cancer cells can be suppressed by UO126, a MEK1/2-specific inhibitor." (PMID 35163805, 2022).
gastric cancer (continued). "It was previously reported that LINC00473 suppressed migration and invasion of gastric cancer cells through regulating expression of Matrix metalloproteinase (MMP)‐2, MMP‐9, E‐cadherin, and Vimentin." (PMID 35600648, 2022). "Based on our results, we reported that sulforaphane suppresses the nicotine-induced MMP-9 by inhibiting ROS-mediated MAPK (p38 MAPK, Erk1/2)/AP-1 and ROS-mediated NF-κB signaling axes, which in turn inhibit cell invasion in human gastric cancer AGS cells." (PMID 35563563, 2022). "Collectively, our study demonstrated that DHCE suppressed gastric cancer cells’ proliferation, migration, and invasion through targeting ERK2 and disrupting the Ras/Raf/ERK/MMP9 signaling pathway." (PMID 35566048, 2022). "A histone lysine methyltransferase, SETDB1, which is upregulated in gastric cancer tissue, interacts with ERG (Ets-related gene) transcription regulator to promote the transcription of MMP-9 and cyclin D1 through binding to their promoter regions." (PMID 35163805, 2022). "PI3K/AKT/mTOR signaling is activated and induces MMP-9 expression in hepatocellular carcinoma and MMP-2 expression in gastric cancer cells." (PMID 36014933, 2022). "In gastric cancer, FENDRR was found to increase cell migration and invasion via up-regulation of FN1, MMP2 and MMP9." (PMID 35183135, 2022). "The levels of serum MMP9 and MMP2 in patients with gastric cancer were significantly higher than normal people in clinical practice." (PMID 35069767, 2022). "In summary, we revealed that DHCE can suppress proliferation, induce apoptosis and G2/M phase arrest in gastric cancer cells, and suppress the migration and invasion of gastric cancer cells by targeting the Ras/Raf/ERK/MMP9 pathway." (PMID 35566048, 2022). "A known antioxidant, N-acetyl-cysteine (NAC), suppressed expression of MMP such as MMP-9 and MMP-2, and cell invasion in pancreatic cancer cells, mammary epithelial cells, and gastric cancer cells." (PMID 36014933, 2022). "The present study suggested that nicotine induces ROS generation in gastric cancer AGS cells, and NAC abrogated nicotine-induced MMP-9 expression." (PMID 35563563, 2022). "MCs exert a pro-tumorigenic role in gastric cancer through the release of angiogenic (VEGF-A, CXCL8, MMP-9) and lymphangiogenic factors (VEGF-C and VEGF-F)." (PMID 35626257, 2022). "The inhibition of TGF-β1 secreted by gastric cancer cells prevented CAF activation through the suppression of α-SMA, MMP-9, TGF-β1, and IL-6." (PMID 35740372, 2022). "In summary, this study showed that SDF-1/CXCR7 enhanced the migration and invasion ability of the gastric cancer cells, increased expressions of MMP-2, MMP-9 and VEGF, promoted EMT and activated the Akt pathway." (PMID 34858476, 2021). "The invasion and migration of gastric cancer cells can be promoted by MMP-2 and MMP-9, which are upregulated by the CXCL10/CXCR3 axis." (PMID 34367971, 2021). "The expression of MMP‐9 was upregulated in Panc‐1‐3P cells and NTSR1‐overexpressing SUIT‐2 cells, which was in accordance with a previous report in gastric cancer cells." (PMID 33034134, 2021). "Transfected SLPI‐siRNA in gastric cancer cell lines resulted in significantly reduced MMP2 and MMP9 expression, as well as cell migration and invasion rates." (PMID 34580954, 2021). "JNJ0966, GS-5745, two chemotherapy drugs, were selective inhibitors regarding matrix metalloproteinase-9 (MMP-9), had shown prospective view in treatment of encephalomyelitis, ulcerative colitis and gastric cancer." (PMID 34261456, 2021). "The expression of BGN, LOX, MMP-9, SERPINE1, and TGFB1 proteins was significantly higher in the samples of gastric cancer patients compared to the healthy people." (PMID 34054953, 2021). "Simvastatin sensitizes gastric cancer to capecitabine in human gastric cancer xenografts by inhibiting NF-κB activation and abrogation of cyclin D1, cyclooxygenase-2 (COX-2), survivin, Bcl-2, CXC motif receptor 4, and MMP-9." (PMID 34065757, 2021).